NAMPT (nicotinamide phosphoribosyltransferase)
Diseases named in the same sentence as NAMPT in open-access papers (continued):
Sharing a sentence is not in itself a finding about the gene and the disease.
tumor (continued). "Accordingly, coupling FK866 therapy to our NAPRT inhibitors would presumably reverse the protective effect of the intestinal bacteria and restore the anti-tumor effect of NAMPT inhibitors in vivo." (PMID 35890147, 2022). "Several studies indicated that the therapeutic activity of NAMPT inhibitors is largely dictated by the NAPRT expression status of the tumor cells." (PMID 35890147, 2022). "In general, NAMPT can promote the progression of tumors and regulate the tumor immune microenvironment." (PMID 35515130, 2022). "Nicotinamide phosphoribosyltransferase (NAMPT) is notable for its regulatory roles in tumor development and progression." (PMID 35565188, 2022). "Regrettably, despite their efficacy in preclinical models, NAMPT inhibitors showed poor efficacy in clinical trials, indicating that tumor cells exploit surrogate NAD-producing routes, in particular the PH pathway, to circumvent NAMPT blockade." (PMID 35890147, 2022). "Any therapeutic strategy aiming to block only one route of NAD+ biosynthesis should therefore be expected to fail in tumor cells in which the enzymatic apparatus of both NAD+ production routes (via NAMPT and via NAPRT) is expressed." (PMID 35396381, 2022). "Inhibition of nicotinamide phosphoribosyltransferase in TANs led to the anti-tumor conversion of neutrophils and attenuated the tumor angiogenesis and growth in a melanoma mouse model." (PMID 35585567, 2022). "NAMPT overexpression generates an increase in NAD+ content in tumour cells, which enhances the activity of NAD+-dependent and NAD+-consuming enzymes (SIRTs, PARPs and cADPRSs)." (PMID 36078035, 2022). "Since tumor cells have a high demand for large amounts of NAD+, inhibiting NAMPT expression can significantly inhibit tumor cell proliferation." (PMID 35680848, 2022). "Similarly, another study showed that nicotinamide phosphoribosyltransferase (NAMPT), a protein implicated in the downstream signaling of the granulocyte colony-stimulating factor receptor (G-CSF-R), is required for vascularization in a transplantable tumor model." (PMID 36060811, 2022). "For example, inhibiting nicotinamide phosphoribosyltransferase expression and suppressing NAD+ synthesis to reduce tumour growth has been reported to be successful in various tumour types, but this is unfortunately associated with severe retinal toxicity." (PMID 35624805, 2022). "Complexes of ruthenium with NAMPT inhibitors have been developed and have been shown to be effective in hypoxic parts of the tumour since the activation process of the prodrug is independent of oxygen concentration." (PMID 36078035, 2022). "The observation of differences in RNA expression in specific tumor types indicates the potentially critical regulatory mechanisms that control the activation or repression of NAMPT at the level of upstream transcriptional activity." (PMID 35565188, 2022). "Lastly, NAMPT inhibition, alone or in conjunction with glycolytic inhibition, was shown to significantly halt tumor growth in-vivo." (PMID 35814452, 2022). "Both in-vitro and clinical data have established an interesting inverse relationship between NAMPT expression and the expression of p73, a tumor suppressor across multiple malignancies." (PMID 35814452, 2022). "The search for novel anti-tumor candidates has led to the development of numerous NAMPT inhibitors, and two compounds FK866 and CHS-828 have entered clinical trials." (PMID 36615364, 2022). "Small-molecule NAMPT inhibitors remarkably eliminate tumor lesions in a short period by downregulating NAD." (PMID 35903330, 2022). "Daporinad (FK866) is one of the highly specific inhibitors of nicotinamide phosphoribosyl transferase (NAMPT) and known to have its unique mechanism of action that induces the tumor cell apoptosis." (PMID 35335372, 2022). "Collectively, these data underscore that the tumor metabolic environment as well as gut microbiota can interfere with the therapeutic efficacy of a NAMPT inhibitor." (PMID 35396381, 2022).
tumor (continued). "NAMPT is capable of increasing the tumorigenic properties of cells, such as cell proliferation, clone formation and resistance to apoptosis, thus allowing tumour initiation and progression." (PMID 36078035, 2022). "On the contrary, we revealed a significant NAMPT CNA at the 7q22 locus where NAMPT mapped in all tumor samples, assessed by array CGH and measured as Segments of Gain Or Loss (SGOL) score (P < 2.2e−16)." (PMID 35272691, 2022). "In the tumor immune microenvironment, NAMPT interacts with inflammatory factors, and many previous studies have shown that extracellular NAMPT promotes the production of many inflammatory factors, such as IL-1α, IL-1β, IL-6, and TNF-α." (PMID 35906622, 2022). "For example, in stomach, colon and glioblastoma cancer, high levels of NAMPT correlate with aggressive tumour stages, metastasis, treatment resistance and worse prognosis." (PMID 36078035, 2022). "An increasing number of studies have proven that targeting NAMPT can be a feasible strategy for inhibiting tumor progression." (PMID 35515130, 2022). "With this review, we aim to shed light on the regulatory roles of NAMPT in tumor development and progression, and provide information to guide future research directions in this field." (PMID 35565188, 2022). "Acting both at the intracellular and extracellular levels, NAMPT exerts a direct role on tumor cells increasing tumor aggressiveness and modifying interactions with the tumor microenvironment." (PMID 35272691, 2022). "Extracellular (e)NAMPT levels are increased in many tumors, suggesting that the molecule is a novel player in tumor–host interactions." (PMID 34073463, 2021). "It is now generally believed that NAMPT is highly expressed in cells with active proliferation, especially tumor cells, which implicates NAMPT-targeted small-molecule inhibitors as potential tumor therapeutic agents." (PMID 34988121, 2021). "The inhibition of both NAMPT activities can repolarize myeloid cells and inhibit tumor growth, especially in combination with immune checkpoint therapies." (PMID 33384409, 2021). "Inhibition of the rate-limiting enzyme NAMPT in the salvage synthesis pathway in tumour cells and animal tumour models has been shown to reduce the growth of tumour cells and enhance survival of animals." (PMID 34881075, 2021). "Nicotinamide phosphoribosyltransferase (NAMPT) is regarded as an important target for tumor treatment, and many studies have confirmed that NAMPT inhibitors have obvious antitumor effects." (PMID 33540574, 2021). "Intriguingly, NAMPT has a second life outside the cell creating immune suppressive and pro-tumor conditions." (PMID 34073463, 2021). "NAMPT activity was also significantly higher in NHATERT tumor tissue relative to NHAALT and tumor-free healthy brain." (PMID 33397920, 2021). "We found that the expression levels of CANX, BIRC5, BID, and NAMPT in tumor tissues were significantly higher than their expression levels in normal tissues, indicating that they are all significantly related to tumor occurrence and development." (PMID 34988121, 2021). "Recently, NAMPT has been reported to orchestrate the redistribution of myeloid cells in tumour-bearing hosts via the NAMPT–NAD+–SIRT1 pathway that promotes the activation of c/EBPα and c/EBP-β-driven G-CSF and G-CSFR gene transcription." (PMID 34685679, 2021). "The NAMPT expression was significantly different in tumor tissues and adjacent tissues in 59 patients, and the paired difference analysis results were consistent (p = 0.002)." (PMID 33540574, 2021). "The xenograft tumor growth curves and the average tumor weight of the shNAMPT-LoVo and shCtrl-LoVo cell groups suggested that the knockdown of NAMPT inhibited CRC proliferation in vivo." (PMID 32005247, 2020). "Nicotinamide phosphoribosyltransferase (NAMPT) drives tumor immune evasion by inducing PD-L1 expression in multiple types of tumors, but enhances the efficacy of immune checkpoint inhibitors." (PMID 33425905, 2020).
tumor (continued). "The authors demonstrated, using transplantable tumor models, that NAMPT is essential for tumorigenic conversion of TANs and their pro-angiogenic switch and inhibition of NAMPT in TANs leads to their antitumor conversion." (PMID 32477131, 2020). "NAMPT inhibitors were primarily developed as anticancer agents, depleting NAD and causing metabolic crash and tumor cell death." (PMID 32266141, 2020). "In the past, NAMPT inhibitors (NAMPTi) showed modest anti-tumor activity mostly because NAMPT block was bypassed by compensation through other NAD-biosynthetic pathways, such as that regulated through NAPRT and NRK." (PMID 33419372, 2020). "Nicotinamide phosphoribosyltransferase (NAMPT) is an important enzyme for tumor nicotinamide metabolism, which catalyzes the biosynthesis of nicotinamide adenine dinucleotide." (PMID 32050640, 2020). "In support of this, NAMPT inhibitors enhance the anti-tumor efficacy of immune checkpoint inhibitors (i.e. antibody against PD-1;." (PMID 32477131, 2020). "NAMPT as a predictive biomarker for tumor-selective targeting of NAD+ metabolism is, therefore, a promising therapeutic strategy." (PMID 32295316, 2020). "NAMPT again showed increased expression in the tumours and was undetectable in all but one of the normal kidney tissue samples." (PMID 32390008, 2020). "This energetic core axis is mainly controlled by the rate-limiting enzyme NAMPT, an important oncogene contributing to tumor dedifferentiation." (PMID 31119097, 2019). "Pharmacological NAD+ depletion by an NAMPT inhibitor reportedly led to tumor cell death followed by ATP depletion." (PMID 31123329, 2019). "Until now, it has been shown that NAMPT stimulates growth of endothelial cells, tumor cells and B cells." (PMID 31717318, 2019). "The knockdown of NAMPT expression dramatically increased the apoptosis of cisplatin‐resistant tumor cells following cisplatin treatment, while minimum effects were observed on A549 cells." (PMID 31025554, 2019). "While NAMPT can be an attractive target, limited data currently exists regarding the expression levels of NAMPT in tumor samples derived from patients with PDAs." (PMID 30856230, 2019). "Our findings indicate that miR-494 acts as a tumor suppressor and has an important effect in suppressing the growth of BC cells through NAMPT." (PMID 31645844, 2019). "BC is frequently associated with elevated levels of nicotinamide phosphoribosyltransferase (NAMPT) in blood and tumor tissue." (PMID 31645844, 2019). "It seemed to lead to tumor growth inhibition (T/Cmin = 0.545) in an HT-1080 xenograft mouse model by the same mode of action as other NAMPT inhibitors." (PMID 31123329, 2019). "A number of selective NAMPT small molecule inhibitors have been demonstrated to exert considerable anti-tumor activity in in vitro and in vivo tumor models." (PMID 31357971, 2019). "Immunohistochemical staining performed on MIB1+ (i.e., proliferating) areas of the tumor confirmed high intracellular levels of NAMPT in live human xenografts in both BiR cell lines." (PMID 29721178, 2018). "In some malignancies, such as sarcomas and gastric thyroid and prostate carcinomas, higher NAMPT expression correlates with deeper tumor invasion and increased metastatic potential and chemotherapy resistance." (PMID 29245920, 2017). "A comprehensive study of NAMPT inhibition in various tumor cell types in vitro and in vivo impressively demonstrated FK866-induced blockade of glycolysis, serine biosynthesis, tricarboxylic acid (TCA) cycle, and alterations in the pentose phosphate pathway." (PMID 28160567, 2017). "The inhibition of NAMPT leads to suppression of tumour cell growth and induction of apoptosis due to NAD+ depletion." (PMID 28420117, 2017). "Based on these results, we identified a gene signature triggered by NAMPT that correlates with tumor stage and poor prognosis." (PMID 29245920, 2017).
tumor (continued). "Here, we describe our results of a global study of NAPRT and NAMPT expression across human tissues and tumor cell lines." (PMID 26675378, 2016). "This is the first work to show the activation of JNK signaling pathway by NAMPT inhibitor in tumor cells." (PMID 28097126, 2016). "To date, a number of novel and potent inhibitors targeting NAMPT have been synthesized that have shown anti-tumor efficacy in tumor models in vitro and in vivo." (PMID 27661117, 2016). "Their results also showed that serum extracellular NAMPT levels correlated with tumor grade and was highest in GBM." (PMID 28097126, 2016). "Herein, we provide a comprehensive study of NAPRT and NAMPT expression across human tissues and tumor cell lines." (PMID 26675378, 2016). "The down-regulation of NAMPT suppresses tumor cell growth in vitro and in vivo and sensitizes cells to oxidative stress and DNA-damaging agents." (PMID 25486521, 2014). "The inhibition of NAMPT also leads to the attenuation of tumor growth and induction of apoptosis due to NAD depletion." (PMID 25486521, 2014). "Several studies also suggest that FK866 specifically inhibits NAMPT in the cell and exhibits anti-tumor activity in preclinical tumor models." (PMID 25486521, 2014). "Particularly, mutations that decrease NAPRT1 expression can predict the usefulness of Nicotinic Acid in tumor treatments with NAMPT inhibitors." (PMID 25201160, 2014). "Inhibiting NAD biosynthesis by blocking the function of nicotinamide phosphoribosyl transferase (NAMPT) is an attractive therapeutic strategy for targeting tumor metabolism." (PMID 25285661, 2014). "In conclusion, we found a decrease in tumor [18F]FLT uptake following treatment with the nicotinamide phosphoribosyltransferase inhibitor APO866." (PMID 23308217, 2013). "APO866 is a new anti-tumor compound which inhibits nicotinamide phosphoribosyltransferase (NAMPT), an enzyme involved in the biosynthesis of NAD." (PMID 23308217, 2013). "It is overexpressed in multiple cancers, and inhibition of NAMPT significantly suppresses tumor cell growth." (PMID 24279986, 2013). "Here, we show that targeting of the β-NAD+ metabolism enzyme NAMPT can increase the tumour cell inhibitory effect of the clinical PARP inhibitor olaparib." (PMID 22933245, 2012). "Tumour cells are more sensitive to NAMPT inhibition and NAD depletion due to increased ATP and NAD consumption." (PMID 21144000, 2010). "Additionally, NAD+ supplements can potentiate tumor-killing function by rescuing defective TUB-mediated NAMPT transcription in tumor-infiltrated T cells." (PMID 40861448, 2025). "Finally, the combination of a NAMPT inhibitor and disulfiram showed significant anti-tumor effects and extended survival in an animal model." (PMID 40280967, 2025). "NAMPT exhibits anti-apoptotic properties and is highly expressed across various tumor types." (PMID 40463392, 2025). "To determine whether the inhibitory effect of PF403 on tumor cells was decreased via NAMPT knockdown, we measured the anti-proliferative effect of PF403 on transfected U87 cells after 24 and 72 h." (PMID 40486861, 2025). "Here, we show that tumor-derived granulocyte colony-stimulating factor (G-CSF) reprograms neutrophils through activation of the NAMPT-NAD signaling axis, leading to cytoskeletal alterations, impaired antibacterial responses, and accumulation of tissue-toxic neutrophil subsets." (PMID 41387444, 2025). "As we have identified that Carba1 prevents CIPN through NAMPT activation, an important consideration is whether Carba1 could accidentally promote tumor growth or interfere with therapeutic doses of PTX in mice." (PMID 41160692, 2025). "NAMPT also regulates tumor immune evasion through a CD8+ T cell-dependent mechanism." (PMID 40775221, 2025). "We demonstrated that NAMPT‐mediated NAD+ biosynthesis induces deacetylation of histone H3 at Lys27 (H3K27), which may be associated with PD‐L1 and bolsters tumor immune evasion." (PMID 39988985, 2025).
tumor (continued). "As expected, visfatin treatment increased both of these activities, indicating that extracellular NAMPT could function as oncogenic factor in tumor cells." (PMID 38308188, 2024). "The NR-NMRK pathway can mediate resistance to NAMPT inhibition in salvage-dependent tumor cells, which could be reversed via dual NAMPT and NMRK inhibition." (PMID 38396769, 2024). "We demonstrate here that the molecular mechanism for engagement of NAMPT in promoting M2‐like TAM polarization in response to tumor‐derived lactate is via HIF‐1α stabilization through providing a NAMPT‐dependent sufficient NAD supply for lactate to pyruvate conversion." (PMID 38308188, 2024). "Notably, secretory ligands SPP1 and NAMPT in CXCL8hiIL1Bhi macrophages played a role in tumorogenesis by sending signals to receptors on stromal and tumor cells." (PMID 39229264, 2024). "Indeed, NAMPT drives INFγ-induced PD-L1 expression and induces tumor immune evasion in a CD8+ T cell-dependent manner." (PMID 38254798, 2024). "Based on these findings, we designed and identified a dual-targeting compound, LZFPN-90, targeting PD-L1 may improve the tumor’s immune microenvironment, and targeting NAMPT can inhibit cell growth, block the cell cycle, and subsequently induce apoptosis." (PMID 38448544, 2024). "In addition, NAMPT exhibits abnormal expression in multiple tumor tissues and is predictive for poor prognosis." (PMID 39408693, 2024). "Thus, NAMPT plays an important role in tumor metabolism and immune modulation and is therefore a potential therapeutic target for treating tumors." (PMID 38448544, 2024). "Additionally, inhibitors of several key metabolic enzymes, such as IDH1(Isocitrate Dehydrogenase 1), IDO1((Indoleamine 2,3-dioxygenase 1), GPX4(Glutathione Peroxidase 4), and NAMPT(Nicotinamide phosphoribosyltransferase), have shown good anti-tumor effects." (PMID 39578429, 2024). "NAMPT can inhibit T-cell-mediated anti-tumor immunity through enzyme-independent functions." (PMID 39684426, 2024). "Inhibition of NAMPT affects the tumor cell cycle and apoptosis." (PMID 38448544, 2024). "Other studies have revealed that NAMPT sustains de novo lipogenesis in PCa cells, with its inhibition significantly reducing fatty acid and phosphatidylcholine synthesis, disrupting essential metabolic processes for tumor growth." (PMID 39796040, 2024). "Furthermore, NMN treatment rescued efferocytosis activity in KO macrophages via increasing NADPH levels, indicating that NAMPT likely promoted efferocytosis activity via an increase in NADPH during tumor progression." (PMID 38308188, 2024). "Moreover, NAMPT regulates macrophage survival and pro-inflammatory activity, contributing to the modulation of the tumor inflammatory microenvironment and promoting tumor cell metastasis." (PMID 39372950, 2024). "However, it is important to note that NAMPT-mediated glycolysis is also required for the antitumor immunity of tumor-infiltrating macrophages." (PMID 38605962, 2024). "Despite promising preclinical results, NAMPT inhibitors have shown limited tumor responses in phase I/II clinical trials, suggesting the need for biomarkers to identify patients who may benefit from these inhibitors." (PMID 39272943, 2024). "Therefore, our study provides an important contribution to explaining how NAMPT overexpression enhances tumor overall resistance to therapy, aggressive phenotype, and decreases patient survival." (PMID 37037593, 2023). "The extent to which the EV-mediated transfer of NAMPT occurs in the tumor microenvironment remains to be determined, and a possible way to examine it will be to quantify differences in NAMPT protein expression levels across single cells within tumor sections." (PMID 37037593, 2023). "Altogether, these data suggest that NAMPT inhibitors may be a new class of molecules for treating BC and, more specifically TNBCs, an extremely aggressive tumor subclass still in need of effective therapeutic strategies." (PMID 37858982, 2023).